SDC1 (syndecan 1)
Diseases named in the same sentence as SDC1 in open-access papers (continued):
Sharing a sentence is not in itself a finding about the gene and the disease.
heart failure (continued). "Therefore, in this study, we investigated the prognostic value of serum syndecan-1 concentration upon admission in patients with heart failure." (PMID 34879094, 2021). "Serum syndecan-1 concentrations, which may indicate injury to the endothelial glycocalyx, predict readmission-free survival in patients with heart failure." (PMID 34879094, 2021). "Syndecan-1, as an emerging biomarker for both heart failure and liver fibrosis, could find its usefulness either in the initial assessment or the long-term prognosis in a large number of patients with concomitant cardiac and hepatic diseases." (PMID 31815014, 2019). "Furthermore, STEMI patients admitted to ICU displayed the highest syndecan-1 plasma levels and high levels of adrenaline, syndecan-1 and sTM were strong predictors of poor outcome, including heart failure and mortality." (PMID 28179016, 2017). "Additionally, the syndecan-1 concentration may be a fluid volume marker for heart failure and may be useful in its management." (PMID 34879094, 2021). "Notably, some data from literature show that higher levels of syndecan-1 were correlated with the symptomatology and severity of heart failure, an elevation of the serum biomarker being more commonly met in patients with NYHA III/IV functional class, compared to those in NYHA I/II." (PMID 31815014, 2019). "In humans, plasma syndecan-1 levels correlate with fibrosis biomarkers, and increased syndecan-1 was associated with an increased risk of the primary outcome in heart failure patients with preserved ejection fraction but not those with reduced ejection fraction." (PMID 31547598, 2019). "Finally, taken into consideration the increased prevalence of heart failure in patients with chronic liver diseases and vice-versa, syndecan-1 seems to be an attractive cardiac and hepatic dual biomarker, ready to be used as a diagnosis as well as a prognosis marker." (PMID 31815014, 2019). "In these patients, with preserved EF, where echocardiographic assessment for heart failure is equivocal, syndecan-1 could represent an early diagnosis marker or it could, at least, guide the clinician towards more advanced explorations if its serum levels are above cutoff values." (PMID 31815014, 2019). "The present study revealed that serum syndecan-1 concentration: 1) was higher in patients with heart failure than in healthy subjects from previous reports, 2) responded promptly to treatment against heart failure, and 3) might predict readmission-free survival in patients with heart failure." (PMID 34879094, 2021). "An interesting study conducted by Liu and coworkers has shown that in patients with heart failure and NIDCM, syndecan-1 level is correlated with fibrosis and inflammatory biomarkers." (PMID 34073616, 2021). "In patients with heart failure with preserved ejection fraction (HFpEF), the plasma concentration of syndecan-1 was not significantly elevated, whereas serum hyaluronan was considerably higher, and it was an independent predictor of a poorer clinical outcome." (PMID 38785504, 2024). "Its role in heart failure due to myocardial ischemia or infarction is not to be neglected, where the protective effects mediated by syndecan-1 are based on its anti-inflammatory properties." (PMID 31815014, 2019).
invasive breast carcinoma (11 papers, 2007 to 2026). A carcinoma that infiltrates the breast parenchyma. "Subtype analysis demonstrated that significantly difference between high and low SDC1 expressed in Breast invasive carcinoma (BRCA), GBM, head and neck squamous cell carcinoma (HNSC), KIRC, Lung adenocarcinoma (LUAD) and Lung squamous cell carcinoma (LUSC)." (PMID 41364407, 2025). "The authors conclude that concomitant expression of epithelial and stromal syndecan-1 seems to identify a group of patients with an unfavorable outcome in invasive breast cancer." (PMID 34952631, 2021). "normal samples revealed that SDC1 mRNA was significantly elevated in invasive breast carcinoma, invasive ductal breast carcinoma, mixed lobular and ductal breast carcinoma, invasive lobular breast carcinoma." (PMID 29340066, 2017). "Oncomine analysis of cancer vs. normal tissue revealed that SDC1 mRNA was significantly over-expressed in invasive breast carcinoma, invasive ductal breast carcinoma, mixed lobular and ductal breast carcinoma, invasive lobular breast carcinoma." (PMID 29340066, 2017). "Sdc1 is aberrantly expressed in stromal fibroblasts of invasive breast carcinomas, leading to an aligned ECM fiber architecture." (PMID 26909794, 2016). "Expression of the cell surface proteoglycan syndecan-1 (Sdc1) is frequently induced in stromal fibroblasts of invasive breast carcinomas." (PMID 26909794, 2016). "A study on pre-invasive breast cancer revealed an inverse correlation between the expression of syndecan-1 and the pro-metastatic microRNA miR-10b, suggesting a potential novel mode of post-transcriptional regulation of syndecan-1." (PMID 26869927, 2016). "For these reasons, we have re-evaluated the prognostic value of syndecan-1 in patients with invasive breast carcinomas." (PMID 18542065, 2008). "Sdc1 is frequently aberrantly expressed by stromal fibroblasts in invasive breast carcinomas." (PMID 26909794, 2016). "Interestingly, previous studies have demonstrated that SDC1 expression is not only limited to cancer cells, but also occurs in the stromal compartment across various tumors, particularly in invasive breast cancer, supporting the importance of interactions between different cell types within the TME." (PMID 41228316, 2025). "This is in accordance with the study conducted by Barbareschi and coworkers, which demonstrated positive correlation of Sdc1 and HER2 in a collective of 254 invasive breast carcinomas." (PMID 17244359, 2007).
malignant mesothelioma (11 papers, 2009 to 2021). A malignant neoplasm of the pleura or peritoneum, arising from mesothelial cells. "Based on ROC curve analyses, Galectin-1, Mesothelin, Osteopontin, NRG1-β1 and shed SDC-1 performed the best diagnostic capacity to distinguish malignant mesothelioma from benign effusions." (PMID 32731396, 2020). "This overexpression of syndecan-1 in malignant mesothelioma cells was also associated with considerable changes in expression of other HSPGs: glypican-3 was upregulated whereas glypican-6 and perlecan both were downregulated." (PMID 24392351, 2013). "In malignant mesothelioma, a connective tissue tumour with partial epitheloid differentiation, syndecan-1 is rarely expressed, and its presence is associated with a more epitheloid phenotype and longer survival." (PMID 22745764, 2012). "To determine the effect of SDC-1 on angiogenesis-related protein secretion of malignant mesothelioma (MM) cells, we analyzed the conditioned medium of SDC-1 overexpressing and SDC-1 silenced cells by Proteome Profiler Array." (PMID 33562126, 2021). "Cell surface expression of SDC-1 indicates favorable prognosis in malignant mesothelioma, whereas high levels of shed, soluble SDC-1, correlates to poor prognosis." (PMID 33562126, 2021). "Accelerated shedding and loss of cell surface SDC-1 is associated with epithelial to mesenchymal transition (EMT) and achievement of a more invasive phenotype in malignant mesothelioma (MM)." (PMID 33562126, 2021). "Further studies are needed to elucidate the precise molecular mechanisms of nuclear SDC1 and its direct involvement in these pathways, as well as to study its possible importance in tumors, such as malignant mesothelioma." (PMID 32664515, 2020). "In malignant mesothelioma cases, shed SDC-1 expression was significantly and positively correlated with HGF (p = 0.02; r = 0.3) and NRG1-b1 (p = 0.001; r = 0.4)." (PMID 32731396, 2020). "We have recently shown that syndecan-1 influences multiple signaling pathways in malignant mesothelioma, a highly aggressive mesenchymal tumor." (PMID 26420915, 2015). "In malignant mesothelioma cells, TGFβ inhibited the nuclear translocation of syndecan-1 in parallel with an antiproliferative effect." (PMID 26420915, 2015). "Stratifying malignant mesothelioma patients in “low” and “high” syndecan-1 level using a cutoff of 100.2 ng/mL resulted in median survival times of 17.0 and 7.8 months, respectively (hazard ratio 2.77, 95% CI 1.35 to 5.68)." (PMID 25147801, 2014). "The pleural effusion levels of syndecan-1 were highest in carcinomas, although patients diagnosed with malignant mesothelioma also had significantly elevated levels compared to benign disease." (PMID 25147801, 2014). "A threefold overexpression of syndecan-1 in malignant mesothelioma largely influenced the whole transcriptome often with a much higher deregulation of individual genes than the syndecan-1 itself." (PMID 24392351, 2013). "We have recently shown that overexpression of syndecan-1 in a malignant mesothelioma cell line influences a multitude of signaling pathways." (PMID 24392351, 2013). "For this purpose we modulated syndecan-1 expression in a human malignant mesothelioma cell line and performed microarray analysis to investigate the effects of syndecan-1 overexpression and silencing on general transcriptional level." (PMID 23144729, 2012). "We have previously shown that overexpression of syndecan-1 in malignant mesothelioma correlates with epithelioid differentiation and inhibition of tumor growth and migration." (PMID 23144729, 2012). "By combining these methods we highlight the most crucial biological processes controlled by syndecan-1 in malignant mesothelioma." (PMID 23144729, 2012). "Our previous data show that overexpression of syndecan-1 inhibits proliferation of malignant mesothelioma; in this paper we also investigated the effect of syndecan-1 silencing on the proliferation rate and cell cycle distribution of these cells." (PMID 23144729, 2012).
malignant mesothelioma (continued). "We detected prominent nuclear syndecan-1 not only in malignant mesothelioma but also in various adenocarcinomas and in neuroblastoma cells." (PMID 19802384, 2009). "We have previously shown nuclear syndecan-1 in many other cell types besides malignant mesothelioma, including benign mesothelial cells, normal dermal fibroblasts, endothelial cells, adenocarcinomas and neuroblastoma cells." (PMID 19802384, 2009). "Taken together, these data suggest that combining measurements of both VEGF and shed SDC-1 in pleural effusions could be a useful prognostic indicator in malignant mesothelioma." (PMID 33562126, 2021). "This has been demonstrated with SDC1 in malignant mesothelioma, and here we may be detecting similar effects on other HSPGs by simply modulating GPC1." (PMID 32180897, 2020). "In malignant mesothelioma, syndecan-1 levels are generally low." (PMID 26420915, 2015). "Furthermore, syndecan-1 in pleural effusions predicted a survival difference for patients with pleural metastatic disease and malignant mesothelioma of 11.2 and 9.2 months, respectively." (PMID 25147801, 2014). "Low levels of shed syndecan-1 predict a more favourable prognosis, showing more than 11 months increased median survival for patients with pleural metastases and 9.2 months for malignant mesothelioma; both are diseases with average median survival times of around, or less than, one year." (PMID 25147801, 2014). "Cell-surface expression of syndecan-1 is relatively low in malignant mesothelioma compared to epithelial malignancies, however, its expression relates to epithelioid differentiation thus correlating to better prognosis, and it is reduced or lost in the sarcomatoid phenotype." (PMID 24392351, 2013). "Thus syndecan-1 and syndecan-2 has been proposed as biomarkers to distinguish malignant mesothelioma from metastatic adenocarcinoma." (PMID 24392351, 2013). "The massive downregulation of SULF-1 after syndecan-1 overexpression in malignant mesothelioma may constitute one mechanism by which syndecan-1 regulates cell growth, by modulating the growth factor binding properties of HSPGs." (PMID 24392351, 2013). "A better understanding of the complex role of syndecan-1 and its molecular interactions in malignant mesothelioma may provide future possibilities to control tumor growth and proliferation." (PMID 23144729, 2012). "Our previous studies also suggest that the ratio between syndecan-1 and syndecan-2 may distinguish a primary malignant mesothelioma from a metastatic adenocarcinoma." (PMID 23144729, 2012). "Furthermore, the presence of syndecan-1 implies a better prognosis of malignant mesothelioma." (PMID 23144729, 2012). "Syndecan-1 (SDC1) is a cell surface heparan sulfate proteoglycan (HSPG), which regulates various signaling pathways controlling the proliferation and migration of malignant mesothelioma and other types of cancer." (PMID 32664515, 2020). "Among these angiogenesis related biomarkers, we demonstrated that Galectin-1, Mesothelin, shed SDC-1 and MMP-7 are biomarkers that discriminated best between malignant mesothelioma and metastatic adenocarcinomas." (PMID 32731396, 2020). "Our data shows that the level of Galectin-1 and mesothelin are significantly higher in MM patients in comparison with metastatic adenocarcinoma patients whereas, shed SDC-1 and MMP-7 levels are significantly decreased in malignant mesothelioma patients." (PMID 32731396, 2020). "Here we show that Malignant mesothelioma patients have significantly higher level of Galectin-1, Mesothelin, Osteopontin, VEGF, shed SDC-1, MMP-7, HGF, NRG1-β1 and TIMP-1 compared to benign patients." (PMID 32731396, 2020). "The levels of shed syndecan-1 were elevated in pleural effusions from both metastatic carcinomas and malignant mesothelioma compared to patients with nonmalignant disease." (PMID 25147801, 2014).
malignant mesothelioma (continued). "Interestingly, some of the interleukins regulated by syndecan-1 in our study, such as IL8 acts also as an autocrine growth factor whereas IL6 induces expression of VEGF in malignant mesothelioma." (PMID 23144729, 2012). "Similarly, cultured malignant mesothelioma cells produce less syndecan-1 than benign mesothelial cells, regardless of their phenotypic differentiation." (PMID 22745764, 2012).
metastatic tumors (11 papers, 2014 to 2024). "This association with disease progression suggests that the loss of SDC-1 function at the cell-surface or cell membrane and thus may facilitate cancer progression and the development of invasive and metastatic disease." (PMID 24524203, 2014). "The changed or altered Sdc1 expression from the malignant epithelial to the reactive stromal cells is crucial for the transformation of a ductal breast carcinoma to the metastatic disease, but it is also found during progression of other malignant tumors." (PMID 30151336, 2018). "In endometrial cancer, epithelial SDC1 expression was significantly lower in advanced stage, high grade, and lymph node metastatic disease." (PMID 26293675, 2015). "Differences in the mRNA and protein expression of Sdc-1 have been noted, as Sdc-1 mRNA was strongly overexpressed in metastatic colon tumors, whereas using immunohistochemistry, metastatic tumors showed a dramatic decrease in staining, while labeling was still strong in the adjacent normal mucosa." (PMID 32477959, 2020). "However, 80% of non-metastatic tumors (p < 0.05) exhibited an overexpression of syndecan 1 mRNA, the average being a more than 3-fold increase, as did 87% of metastatic tumors (p < 0.05), although in this case the mean increase was around 70%." (PMID 29940912, 2018). "However, syndecan-1 mRNA appeared overexpressed approximately 8 fold in metastatic tumors only (p = 0.02), the overexpression occurring in 90 % of the metastatic CRCs analyzed." (PMID 26482785, 2015). "Analyzing the expression of syndecan-1 protein using immunohistochemistry, provided the noteworthy finding that non-metastatic CRCs displayed similar immunoreactivity to that detected in normal tissues from the same patients, while the metastatic tumors showed a dramatic decrease in staining." (PMID 26482785, 2015). "Additional studies showed reduced expression of the SDC1 gene and protein in metastatic HCC patients compared to those with non-metastatic disease." (PMID 26293675, 2015). "Moreover, MMP‐7 levels correlated with more advanced, metastatic disease and the combination of MMP‐7 and SDC1 demonstrated prognostic value in PDAC." (PMID 39263943, 2024). "Right-sided colorectal cancers show that the expression of the HSPGs glypican-1,-3, and -6 and betaglycan are altered in non-metastatic tumors, whereas in metastatic tumors, only glypican-1 and SDC1 are modified." (PMID 30197623, 2018).